APC (APC regulator of Wnt signaling pathway)
Diseases named in the same sentence as APC in open-access papers (continued):
Sharing a sentence is not in itself a finding about the gene and the disease.
breast cancer (continued). "The APC promoter methylation was associated with cancer stage (OR = 0.47, 95% CI = 0.28–0.80, P = 0.006), lymph node metastases (OR = 0.55, 95% CI = 0.36–0.84, P = 0.005) and ER status (OR = 1.34, 95% CI = 1.03–1.73, P = 0.003) in breast cancer." (PMID 27191268, 2016). "Hence, we conducted a meta-analysis to investigate the association between breast cancer and APC methylation." (PMID 27191268, 2016). "This was suggesting a good diagnostic accuracy of APC promoter methylation in breast cancer." (PMID 27191268, 2016). "For stratified analysis by ethnicity, the APC methylation showed statistically significant association with increased risks of breast cancers in Caucasians (OR = 3.08, 95% CI = 1.92–4.96, P < 0.00001) and in non-Caucasians (OR = 18.75, 95% CI = 4.12–85.28, P < 0.00001)." (PMID 27191268, 2016). "However, although these mouse models that upregulate the canonical WNT signaling activity induce mammary gland tumors, APC mutations are less frequently found in human breast cancers." (PMID 25406066, 2014). "Although Wnt overexpression may not be responsible for the hyperactive Wnt signaling in human breast cancers, targeting this pathway upstream of mutated APC or β-catenin has also been used since recent evidence suggest that such compounds might be beneficial." (PMID 23457599, 2013). "We did not observe statistically significant association with the risk of developing breast cancer for the SNPs in APC, DKK4 and LRP6 as well as some of the SNPs in β-catenin (rs13072632), AXIN2 (rs4791171, rs11079571 and rs3923086) and SFRP3 (rs288326) in the overall study population." (PMID 23516639, 2013). "However, somatic mutations of APC and β- catenin are infrequently reported in breast cancers, in contrast to findings in colorectal cancers." (PMID 11437404, 2001). "The results indicated that APC variant V1125A and R414S might be the oncogenic and the kinase genes association of survival in breast cancer patients which provides novel target for the development of breast cancer and identifies APC as a novel putative target for targeted therapy." (PMID 35936696, 2022). "We analyzed 2293 samples from 15 studies to assess whether the abnormal APC methylation was associated with breast cancer clinicopathological characteristics, including cancer stage, cancer grade, lymph node metastasis, menopausal status, ER status, PR status and HER2 status." (PMID 27191268, 2016). "Therefore, there were 26 case-control studies for the relationship of APC promoter methylation and breast cancer risk, and 15 cohort studies related with the association between APC methylation and clinicopathological characteristics of breast cancer." (PMID 27191268, 2016). "Also, we are searching whether FAP patients with APC germline mutations in the proximity of codon 1600 show any eventual predisposition to breast cancer." (PMID 19578404, 2009). "Consistently, in the CPTAC human breast cancer dataset, the protein levels of Geminin, a well-characterized APC/CCDH1 substrate, were positively correlated with PIN1 protein abundance, whereas low levels of APC/CCDH1 were associated with poor prognosis of BC." (PMID 38622115, 2024). "By contrast, APC depletion in breast cancer cells appeared to increase their degradative potential in a 2D setting." (PMID 38680662, 2024). "Our studies are the first to show that Bcl-2 functional inhibition restores PTX sensitivity in APC mutant breast cancer cells." (PMID 38928449, 2024).
breast cancer (continued). "For some genes, single P/LP variants were detected either only in the group of patients with breast cancer (APC, MDM1, MRE11, POLD1, NF1, RAD51C, RECQL4, and WRN) or only in the control group (MCPH1, MSH3, and XPC)." (PMID 39684352, 2024). "We demonstrated decreased APC mRNA and protein levels in breast cancer patients compared with normal tissue." (PMID 37108784, 2023). "To establish the clinical relevance of the loss of APC in breast cancer, by using the TCGA and CPTAC databases, we showed that APC mRNA and protein levels are decreased in primary human breast tumors compared with normal tissue." (PMID 37108784, 2023). "One of the first studies that proposed the use of epigenetic biomarkers in plasma to detect breast cancer compared four methylation biomarkers, APC, GSTP1, RASSF1A, and RARB, in primary breast cancer tissue and plasma samples." (PMID 36765815, 2023). "Among these, four genes (APC, GSK3B, GSNK2B, GSNK2A2) are negative regulators of WNT signalling with deletions that are associated with metastasis in breast cancer patients after NAC exposure." (PMID 37345102, 2023). "It has been described that genetic alterations in Wnt pathway components, such as APC, β-catenin, AXIN2, and TCF7L2 are implicated in colorectal, melanoma, gastric, hepatocellular, and breast cancer." (PMID 35996498, 2022). "Binding of EB1 to APC in the cortex of breast cancer cells controls APC-mediated actin assembly and, moreover, perturbation of normal EB1 levels, up or down, disrupts directional cell migration." (PMID 35903547, 2022). "APC promoter hypermethylation also can be a prognostic marker for breast cancer, and high expression of APC is an unfavorable prognostic biomarker for T4 gastric cancer." (PMID 35303016, 2022). "We first reported that APC somatic mutations (V1125A and R414S) were enriched in TNBC and associated with reduced overall survival in all breast cancer patients." (PMID 35936696, 2022). "As for the breast cancer samples, the pathway module 8 contained several well-known driver mutations, including KRAS, APC, and ARID1A." (PMID 33819263, 2021). "As tumor suppressor factors, TGFβRII or SMAD4 knockout significantly accelerated progression of malignant tumors; examples include APC inactivation in intestinal polyps, PyMT-induced breast cancer, and pancreatic injury induced by Kras." (PMID 34095135, 2021). "A PV in the APC gene, (c.3920T > A, p.(Ile1307Lys) was detected in 5 unrelated patients with breast cancer." (PMID 34326862, 2021). "Three women had bilateral breast cancer with VUS in APC, ATM, and BRCA2, 2 of whom were diagnosed before the age of 50 years." (PMID 33646313, 2021). "By treating breast cancer cells presenting hypermethylated APC with genistein, the methylation-induced silencing in APC was reversed." (PMID 33968756, 2021). "Among other genes with a prevalence of PVs >1% were APC (1.12%), involved in hereditary colorectal cancer, the breast cancer genes PTEN and BRCA1 (1.61%, 1.06%), and FANCA (1.04%), involved in Fanconi anemia." (PMID 34255164, 2021). "Epigenetic silencing of WNT/β‐CATENIN antagonists is frequently observed in breast cancer, and reduced expression of APC, CDH1, SFRP1 and SFRP2 due to promoter hypermethylation has been reported in many breast tumours." (PMID 33462997, 2021). "The aggressiveness of breast cancer is associated with high promoter methylation of TWIST, SFRP1, ESR1, P16, and APC in lymph node positive breast cancer cases." (PMID 32183060, 2020). "The upregulation of miR-135 induced paclitaxel resistance via downregulating APC in lung, uterine, and breast cancer cells." (PMID 33105836, 2020).
breast cancer (continued). "We have also shown enhanced mammosphere development in a model of APC-knockdown human breast cancer cells (unpublished results)." (PMID 33105836, 2020). "While the knockdown of APC in mBCSCs decreased DNA damage, increased BER activity, and reduced apoptosis, the overexpression of APC in BT20 breast cancer cells displayed the opposite affects." (PMID 33105836, 2020). "Similar to CRC, the APC tumor suppressor gene also plays a significant role in breast cancer carcinogenesis." (PMID 33266025, 2020). "The mouse mammary carcinoma cells referred to as 4T07 showed APC/β-catenin complexes at membrane protrusions." (PMID 33105836, 2020). "Here, we report likely pathogenic and pathogenic variants in APC and PALB2 in cases of co‐occurrence of breast cancer and NET." (PMID 31592449, 2019). "The first cases of a PALB2, an APC and a NTHL1 pathogenic variants in patients with both breast cancer and NET were presented." (PMID 31592449, 2019). "Five of these genes were found to be significantly methylated in breast cancers from our cohort in Senegal (APC, RASSF1, GASTP1, SCGB3a1, and HS3ST2)." (PMID 31819783, 2019). "Some methylation markers commonly used for monitoring breast cancer, including APC, RASSF1A, and RARβ, predominantly displayed patterns consistent with homogeneous methylation." (PMID 30154364, 2018). "In the present study, we found that the improved survival after breast cancer with high RPA was greatest among patients with methylated APC, CCND2, HIN1, and TWIST1 promoters." (PMID 28222775, 2017). "Loss of APC in the MMTV-PyMT mouse model increases activation of STAT3, which is constitutively activated in approximately 50% of breast cancer cell lines and tumor samples." (PMID 29262529, 2017). "In the case of breast cancer, we have found three exclusive pathways, including Cdc20: phospho-APC/C mediated degradation of cyclin A, regulation of beta-cell development and biological oxidations." (PMID 29020948, 2017). "In the 965 TCGA breast cancer samples, the genomic APC regions was lost in 108 samples (11.3%), APC2 in 91 (9.5%) and concurrent loss of APC and APC2 was seen in 35 (3.7%) of samples." (PMID 27694902, 2017). "Our data showed that the frequency of APC promoter methylation was demonstrated to be 5.92-fold high in breast cancer patients compared with non-breast cancer groups." (PMID 27191268, 2016). "Further studies should be needed to investigate the frequency of APC methylation in breast cancer types." (PMID 27191268, 2016). "Axin1, recently determined to be a critical protein that is downregulated in breast cancer, targets β-catenin for degradation when complexed with APC, GSK-3β, and CKII." (PMID 26908451, 2016). "In two human breast cancer lines, folate leads to methylation-mediated silencing of APC and other tumour suppressor genes, raising concern about the risk of tumour progression." (PMID 26861414, 2016). "In this study, we found that the frequency of APC methylation was significantly higher in breast cancer than normal controls." (PMID 27191268, 2016). "This meta-analysis showed that pooled sensitivity and specificity for all included studies were 0.444 and 0.976 respectively, suggesting that the APC promoter methylation is a valuable biomarker for diagnosis of breast cancer." (PMID 27191268, 2016). "Even though there were lots of investigations, the relationships between APC promoter methylation and breast cancer are still controversial." (PMID 27191268, 2016). "The odds ratio (OR) of APC methylation was 5.92 (95% CI = 3.16–11.07) in breast cancer cases compared to controls." (PMID 27191268, 2016).
breast cancer (continued). "The AUC in all samples, tissue samples and blood samples analysis was 0.81, 0.79 and 0.85, which suggested that it is more appropriate to monitor the level of APC methylation in blood samples for the diagnosing breast cancers." (PMID 27191268, 2016). "Herein we report that APC loss-of-function in cells from the MMTV-PyMT mouse model and metaplastic human breast cancer cell line MDA-MB-157 results in resistance to chemotherapy-induced apoptosis." (PMID 26049416, 2015). "This is a significant finding that has the potential to eliminate chemotherapeutic resistance in APC-mutant breast cancers." (PMID 26049416, 2015). "Results from the human metaplastic breast cancer cell line MDA-MB-157 showed APC knockdown resulted in resistance to apoptosis in both cisplatin and paclitaxel." (PMID 26049416, 2015). "Lastly, we measured the apoptotic and proliferative response to APC knockdown in MDA-MB-157 human breast cancer cells after chemotherapeutic treatment." (PMID 26049416, 2015). "Previous studies have only addressed the expression of β-catenin protein in spontaneous canine mammary tumors in relation to E-cadherin and/or APC." (PMID 24887235, 2014). "In contrast, epigenetic silencing of APC and Wnt ligand inhibitors (sFRP1 and Wif1) have often been reported in primary human mammary tumors and in human breast cancer cell lines." (PMID 24887235, 2014). "We further confirmed that consistent with the results of the human breast cancer cell lines, the protein level of APC was elevated in the human breast cancer cells isolated from the anti-miR-142-3p-expressing breast cancer xenograft." (PMID 25406066, 2014). "Elevated levels of nuclear and/or cytoplasmic β-catenin have been reported in a large portion of breast tumor tissue samples (60%), although genetic alterations in Axin, APC and β-catenin in breast cancer are extremely rare." (PMID 23516639, 2013). "Using an in vitro model of APC depletion in the 4T07 mouse mammary tumor cells, we demonstrate that disruption of these complexes inhibits tumor cell migration and disrupt mesenchymal cell morphology." (PMID 23302090, 2013). "In particular, RASSF1A methylation of cfDNA predicted the presence of breast cancer with a sensitivity ranging from 15% to 75%, whereas with APC, methylation sensitivities from 2% to 47% were achieved." (PMID 23320751, 2013). "APC expression was knocked down in 4T07 mammary tumor cells using lentiviral-mediated delivery of APC-specific short-hairpin (sh) RNAs, and assessed using quantitative (q) reverse-transcriptase (RT)-PCR and western blotting." (PMID 23302090, 2013). "To determine the importance of APC/β-catenin-containing complexes at the protrusions in mammary tumor cell behavior, we stably suppressed APC expression using lentiviral-mediated expression of APC shRNAs." (PMID 23302090, 2013). "Human breast cancer cells, including the ER-negative Hs578T line, showed the identical pattern of APC/β-catenin co-localization at protrusion ends." (PMID 23302090, 2013). "Altogether our study demonstrates that Axin stabilization via inhibition of tankyrases can inhibit Wnt signalling in certain breast cancer cells harboring normal APC." (PMID 23144924, 2012). "Fourth, an increased frequency of mammary tumors was found in both MUTYH- and APC-deficient mice compared to mice with an APC deficiency only." (PMID 22297469, 2012). "Promoter methylation of the APC gene has been found in about 40% of breast cancer cases, and high levels of promoter methylation for several Wnt-inhibitory genes in the SFRP and DKK families in breast cancer have also been reported." (PMID 21304988, 2011).
breast cancer (continued). "Notably, DU4475, a human breast cancer cell line derived from a recurrent thoracic wall tumor following mastectomy due to a poorly differentiated invasive ductal carcinoma, carries a nonsense mutation at codon 1577 of the APC gene, only 5 residues downstream of the targeted Apc1572T allele." (PMID 19578404, 2009). "Many components of Wnt/β-catenin signaling pathway also play critical roles in mammary tumor development, yet the role of the tumor suppressor gene APC (adenomatous polyposis coli) in breast oncongenesis is unclear." (PMID 19197353, 2009). "Mutations and/or altered expression in the tumor suppressor gene APC are frequently found in sporadic breast cancers which implicates its role as a tumor suppressor in mammary epithelium." (PMID 19197353, 2009). "As observed in the vast majority of the intestinal and extra-intestinal tumors caused by APC gene mutations in man and mouse, LOH analysis of DNA and protein samples from Apc+/1572T mammary tumors revealed allelic imbalance in more than 90% of cases (21/23)." (PMID 19578404, 2009). "In breast cancer, we recently demonstrated that SNPs in the AXIN2 and APC genes are associated with risk." (PMID 19732438, 2009). "Many components of Wnt/β-catenin signaling pathway are known to play critical roles in mammary tumor development, yet the role of the tumor suppressor gene APC (adenomatous polyposis coli) in breast oncongenesis is unclear." (PMID 19197353, 2009). "In contrast to colorectal cancer (CRC), however, mutation of APC, AXIN or CTNNB1 (β-catenin) is rare in breast cancer, indicating that other mechanisms are responsible for the activation of β-catenin." (PMID 18283316, 2008). "In most cultured breast cancer cells, there is a complete concordance between APC promoter methylation and silencing of its transcript." (PMID 18841156, 2008). "The frequency of APC methylation in our series of primary breast cancers was consistent with that recently reported by others." (PMID 18841156, 2008). "Nevertheless, epigenetic inactivation of APC due to DNA methylation is frequently present in both breast cancer cell lines and breast cancer tissue." (PMID 18841156, 2008). "Of the 10 breast cancers with low APC methylation status by qMSP, eight (80%) expressed APC protein." (PMID 18841156, 2008). "There was a significant correlation of APC promoter hypermethylation with the histological grade of the tumour (P=0.034; χ2) and with tumour stage (P=0.026; χ2) in our series of breast carcinomas (n=51)." (PMID 18841156, 2008). "Methylation of the cyclin D2 promoter appeared to be specific to breast cancer, however, promoter methylation of APC, RARbeta2 and RASSF1A in normal breast from breast cancer patients was associated with increased breasts cancer risk." (PMID 17362521, 2007). "Its expression by APC was recently supposed to be correlated to a better prognosis in breast cancers." (PMID 15756258, 2005). "For examples, the insertions cause heamophilia B (factor IX gene), neurofibromatosis (NF-1 gene), Apert syndrome (FGFR2 gene), acholinesterasemia (ChE gene), desmoid tumors (APC gene) and breast cancer (see the review by Kazazian, 1998)." (PMID 12610505, 2003). "Furthermore, methylation of tumor suppressor genes such as CDH1, APC, CTNNB1, and 14-3-3 Sigma is associated with breast cancer growth." (PMID 40809180, 2025). "In addition, we also found that SETDB2 knockdown diminished the interaction between CDC20 and BUBR1 or APC3 (APC/C complex component protein) in MCF7 breast cancer cells." (PMID 38151757, 2024). "Time-course inhibition experiments coupled to Western blot analysis confirmed that interfering with APC/C activation by Cdc20 in breast cancer cells treated with APN and Cbz-APN impaired the proteolytic degradation of the genuine APC/C substrates Cyclin B and Cdc20." (PMID 39595615, 2024).